AREG (amphiregulin)
Diseases named in the same sentence as AREG in open-access papers (continued):
Sharing a sentence is not in itself a finding about the gene and the disease.
melanoma (continued). "Due to the robust upregulation of AREG and its role in the tumor progression of different cancer types, which highlights its suitability as a therapeutic target, we further examined whether AREG mediates the effects of induced CD133 expression in melanoma stem cells." (PMID 38727313, 2024). "Therefore, we investigated whether amphiregulin augmented the progression of malignant melanoma in vivo by using SK-MEL-28 cells overexpressing amphiregulin, SK-amphiregulin cells." (PMID 30718742, 2019). "However, it remained to be clarified whether expression of amphiregulin enhanced the tumorigenicity of malignant melanoma." (PMID 30718742, 2019). "In addition, in order to investigate whether the increased expression of amphiregulin in melanoma cells is cell-autonomously regulated by IL13Rα2, we studied the amphiregulin expression in various melanoma cells in which IL13Rα2 expression was altered." (PMID 30718742, 2019). "The clinical correlation between AREG and COX‐1/COX‐2 expression in melanoma further supports targeting prostaglandin synthesis (e.g., COX inhibitors) as a strategy to disrupt this axis." (PMID 41082397, 2026). "In previous studies, we showed that molecules such as melanoma inhibitory activity (MIA) and amphiregulin (AREG) are important factors for maintaining senescence in melanocytes." (PMID 38388496, 2024). "In summary, AREG supports and stabilizes OIS in melanocytes, e.g., in nevi, and therefore plays an important tumor-suppressive function in early melanoma development as a component of the SASP." (PMID 33562468, 2021). "We showed that expression of IL13Rα2 in the malignant melanoma SK-MEL-28 cells increased expression of angiogenic factor, amphiregulin as well as enhanced tumour angiogenesis and tumorigenicity in vivo." (PMID 30718742, 2019). "AREG RNA and protein levels in both BAKP and POT melanoma cells are therefore markedly elevated in response to CD133 upregulation, resulting in enhanced levels of the transmembrane precursor as well as the secreted mature ligand forms of AREG." (PMID 38727313, 2024). "Immunofluorescence analysis further reveals that AREG is localized in the cytoplasm and cell membrane and not in the nuclei of melanoma cells." (PMID 38727313, 2024). "Increased expression of IL13Rα2 in A2058 and SK-MEL-28 melanoma cells, which do not express endogenous IL13Rα2, the expression of amphiregulin was upregulated." (PMID 30718742, 2019). "We showed that IL13Rα2 expression not only enhanced the expression of amphiregulin but also suppressed in vitro proliferation of SK-MEL-28 cells, suggesting that IL13Rα2 transduces intracellular signals that regulated these events in melanoma cells." (PMID 30718742, 2019). "We also found that the expression of amphiregulin, a member of the epidermal growth factor (EGF) family, was correlated with IL13Rα2 expression in cultured melanoma cells, xenograft tumour tissues and melanoma clinical samples." (PMID 30718742, 2019). "A potential mechanism of ERBB activation in Class II melanomas is minimal expression of the ERK1/2 phosphatase, DUSP4, as ectopic restoration of DUSP4 attenuated ERBB signaling through potential modulation of the ERBB ligand, amphiregulin (AREG)." (PMID 26084293, 2015). "Previously, ‘driver-negative’ (i.e. the absence of BRAF, NRAS, KIT, GNAQ or GNA11 mutations) melanoma cell-lines that were less sensitive to trametinib and which displayed paradoxical activation of MEK1/2, were found to show basal EGFR activation due to AREG." (PMID 35993275, 2022). "Furthermore, in order to determine whether IL13RA2 expression level in melanoma clinical samples was correlated with AREG expression, we analysed IL13RA2 and AREG expression by using the TCGA (The Cancer Genome Atlas) database." (PMID 30718742, 2019).
glioma (11 papers, 2010 to 2024). A benign or malignant brain and spinal cord tumor that arises from glial cells (astrocytes, oligodendrocytes, ependymal cells). "For example, EGFR ligand amphiregulin from glioma-associated microglia stimulated glioma invasion." (PMID 35053605, 2022). "Recently we demonstrated that CSF-1R mediates invasion in part, via upregulation of the gene Amphiregulin/AREG that presumably acts in a paracrine fashion to induce invasion of glioma cells." (PMID 36982211, 2023). "We focused our attention on the ligand Amphiregulin and its potential function in promoting glioma invasion." (PMID 34843542, 2021). "This induction of AREG expression is important for cell invasion as interfering with AREG either by RNAi-mediated depletion or using function blocking antibodies, attenuates the ability of microglia and macrophages to stimulate glioma invasion." (PMID 34843542, 2021). "We also examined the role of AREG in a human in vitro glioma model." (PMID 34843542, 2021). "We measured the ability of glioma cells to stimulate AREG expression in microglia in coculture." (PMID 34843542, 2021). "Also, it was shown that AREG overexpression is related to glioma cell line resistance to cannabinoid therapies, which induce apoptosis of tumor cells." (PMID 33227903, 2020). "In rat C6 glioma cells, the level of expression of the EGFR ligand amphiregulin is a factor determining the degree of resistance of the cells to the deleterious effects of cannabinoids." (PMID 21203460, 2010). "Tumor-associated microglia promoting glioma cell invasion can be mediated by CSF-1R signaling on gliomas, a pathway involving CSF-1 signaling via ERK that upregulates the expression of dual-regulatory proteins (AREG) in microglia, which are ligands for epithelial growth factor receptor (EGFR)." (PMID 37700840, 2023). "In human U373-MG glioblastoma cells, cannabinoids induce a cell proliferation that is dependent upon the EGFR signalling pathway and in C6 rat glioma cells, expression of the EGFR ligand amphiregulin is an important factor controlling their resistance to the apoptosis produced by cannabinoids." (PMID 20808855, 2010). "This agrees with our findings that the global transcriptomic profiles between RMPAhigh gliomas with or without EGFR alteration were highly similar, and that EGFR ligand AREG and EGF were enriched in the RMPAhigh gliomas." (PMID 27385209, 2016).
liver fibrosis (11 papers, 2010 to 2025). "In mouse liver fibrosis caused by carbon tetrachloride, Kupffer cells showed higher AREG expression and played an important role in liver fibrogenesis." (PMID 37868614, 2023). "In this respect, AREG-deficient mice were found to be protected against liver fibrosis induced by chronic administration of carbon tetrachloride (CCl4)." (PMID 35326439, 2022). "For example, overexpression of HB-EGF and AREG causes pancreatic fibrosis, while high levels of AREG alone are sufficient to trigger liver fibrosis." (PMID 35326439, 2022). "Taken together, these results show that targeting AREG is a feasible approach for liver fibrosis treatment." (PMID 40725192, 2025). "Previous researches have also showed that AREG was involved in several organ fibrosis diseases such as lung and liver fibrosis." (PMID 35996142, 2022). "Here, using a carbon tetrachloride (CCl4)-induced liver fibrosis model, we investigated the dynamics of cellular and molecular signatures in the inflamed liver regulated by Treg cells and Treg-specific amphiregulin." (PMID 33178216, 2020). "TGF-α has previously been shown to increase in previous reports of rats and humans and AREG has previously been shown to participate in the development of mouse liver fibrosis." (PMID 20618941, 2010). "The involvement of AREG in regulating inflammation and promoting tissue repair has been reported in diverse pathologies, including chronic respiratory diseases, liver fibrosis, and autoimmune diseases such as rheumatoid arthritis and systemic lupus erythematosus." (PMID 39451251, 2024). "It remains to be ascertained whether these epiregulin deficient mice would phenocopy the AREG–/– mice and the HB-EGF–/– mice in models of liver fibrosis." (PMID 33520984, 2020). "This shows that excessively active reparative response by AREG participates in liver fibrosis." (PMID 31649806, 2019). "This is consistent with previously reported observations that other members of the EGF family including EGF, heparin-bound EGF (HB-EGF), FGF, and amphiregulin all contribute to HSC trans-differentiation and liver fibrosis." (PMID 33520984, 2020). "Previously it has been shown that amphiregulin (AR), an EGFR ligand closely related to epiregulin (EREG), is activated during HSC trans-differentiation and contributes to liver fibrosis." (PMID 33520984, 2020). "Additionally, the dual-regulatory protein of Tregs known as amphiregulin (AREG) can activate hepatic stellate cells (HSCs) via the EGFR signaling pathway, thereby promoting liver fibrosis and insulin resistance in MASH." (PMID 39917294, 2025).
cervical carcinoma (9 papers, 2015 to 2022). A carcinoma arising from either the exocervical squamous epithelium or the endocervical glandular epithelium. "Overexpression of ANO4 or ANO9 in human cervical cancer cells (HeLa), enhanced constitutive shedding of the growth factor AREG and increased cell proliferation." (PMID 35207044, 2022). "E6 suppresses YAP degradation and promotes nuclear YAP localization, thereby increasing growth-related genes, including amphiregulin (AREG) and transforming growth factor alpha (TGFA), which encode TGF-α, in cervical cancer." (PMID 36294681, 2022). "Activated YAP triggers the amplification of EGFR, AREG and TGFα, and therefore a positive loop is formed that promotes cervical cancer progression." (PMID 33467099, 2021). "Remarkably, we found that treatment of cervical cancer cells with AREG resulted in a fourfold increase in the expression of AREG mRNA (P > 0.001)." (PMID 26417066, 2015). "We also found that AREG significantly stimulated cervical cancer cell proliferation and promoted cancer cell migration." (PMID 26417066, 2015). "RNA sequencing data extracted from TCGA datasets also showed that TGF-α mRNA level was significantly correlated with AREG mRNA expression in cervical cancer (P = 0.0003, Fig EV3)." (PMID 26417066, 2015). "Most interestingly, we found that the AREG mRNA expression was induced by AREG itself in cultured ME180 cervical cancer cells (Fig7D)." (PMID 26417066, 2015). "Intriguingly, AREG was able to suppress phosphorylation of LATS1, MOB1, and YAP in the cervical cancer cells, suggesting that AREG is not only a downstream target of the Hippo pathway, but also an important upstream regulator of the Hippo/YAP signaling pathway." (PMID 26417066, 2015). "Finally, knockdown of LATS1/2, the major suppressors of YAP, results in dephosphorylation of YAP in ME180 cervical cancer cells, leading to the significant increase in the cell proliferation and AREG secretion in both 2D and 3D culture systems." (PMID 26417066, 2015). "Meanwhile, it has also been reported that TGF-α and amphiregulin inhibit the Hippo signaling pathway and activate YAP through EGFR to induce the proliferation and migration of cervical cancer cells." (PMID 35070983, 2021). "Activation of YAP1 in cervical cancer cells significantly stimulated the expression of EGFR and its ligands TGFα and AREG." (PMID 30840887, 2019). "In turn, TGFα and AREG, via EGFR signaling, suppressed the Hippo pathway and activated YAP protein (dephosphorylated LATS1, MOB1, and YAP1) to promote cervical cancer cell growth." (PMID 30840887, 2019). "TGF-α and amphiregulin (AREG), via EGFR, inhibit the Hippo signaling pathway and activate YAP to induce cervical cancer cell proliferation and migration." (PMID 26417066, 2015). "Amphiregulin (AREG), a known YAP target gene, was up-regulated by YAP in cervical cancer ME180 cells (Figs5A and EV2A)." (PMID 26417066, 2015). "Activated YAP allows for up-regulation of TGF-α, AREG, and EGFR, forming a positive signaling loop to drive cervical cancer cell proliferation." (PMID 26417066, 2015). "Indeed, the protein levels of a disintegrin and metalloproteinase 17 (ADAM17), amphiregulin (AREG), ECM metalloproteinase inducer (EMMPRIN), and MMP were increased in cervical carcinoma clinical samples when compared with normal adjacent cervical tissues." (PMID 30208169, 2018). "Mechanistically, YAP expression is correlated with human papillomavirus (HPV) integration status and is required for the upregulation of TGF-alpha, amphiregulin (AREG), and EGFR, thereby forming a positive signaling loop to drive cervical cancer cell proliferation." (PMID 30344797, 2018). "Secondly, both TGF-α and AREG dephosphorylate MOB1, LATS1, and YAP in cervical cells (Figs6 and 7), suggesting that the Hippo pathway is actively involved in the EGFR pathway regulation of cervical cancer progression." (PMID 26417066, 2015).
cervical carcinoma (continued). "It is of interest to note that, by binding and activating EGFR, both AREG and transforming growth factor α (TGFα) induce the dephosphorylation of LATS1, MOB1 and YAP in the Hippo signaling pathway, thus activating YAP that drives the proliferation and migration of cervical cancer cells." (PMID 33467099, 2021). "The synergetic suppressive effect of AG1478 and verteporfin on the growth of ME180-YAP and ME180-YAPS127A cells and secretion of AREG clearly indicates that combined targeting of Hippo/YAP and EGFR pathways may represent a novel therapeutic strategy for cervical cancer (Figs8 and EV5)." (PMID 26417066, 2015). "Since AREG is a member of the family of the EGF-like ligands and we have shown that the EGFR pathway interacts with the Hippo pathway to regulate cervical cancer cell growth, we infer that AREG may also be involved in the regulation of cervical cancer cell proliferation." (PMID 26417066, 2015).
multiple myeloma (9 papers, 2016 to 2024). "Multiple myeloma-derived exosomes were found to contain large amounts of amphiregulin (AREG) and induce osteoclastogenesis." (PMID 37627055, 2023). "A heparin-binding factor in EGF family, amphiregulin (AREG) is overexpressed in primary myeloma cells and can promote growth of bone marrow stromal cell." (PMID 27405725, 2016). "In addition, multiple myeloma-derived epidermal growth factor receptor (EGFR) ligand amphiregulin-enriched exosomes were shown to promote EGFR pathway activation, inhibit osteoblast differentiation, and induce osteoclastogenesis." (PMID 32400849, 2020). "Recent studies have highlighted a key role of EVs in this pathogenesis mechanism, both in bone metastatic NSCLC, where increased plasma levels of AREG are correlated with poor prognosis, and in multiple myeloma, a highly osteoclastogenic disease where AREG is a known tumour growth factor." (PMID 33228060, 2020). "In our cellular interaction analysis, myeloma cells displayed an upregulation of inflammatory cytokines (e.g., CCL3, GRN, AREG, and MIF) that target receptors primarily expressed in the myeloid and dendritic cell compartment." (PMID 34845188, 2021). "Amphiregulin (AREG) in multiple myeloma-derived exosomes results in the activation of epidermal growth factor receptor (EGFR) ligand in pre-osteoclasts and is involved in multiple myeloma-induced osteoclastogenesis." (PMID 36678850, 2023).
non-small cell lung carcinoma (9 papers, 2007 to 2025). A group of at least three distinct histological types of lung cancer, including non-small cell squamous cell carcinoma, adenocarcinoma, and large cell carcinoma. "Importantly, AREG overexpression has been identified as a key mechanism underlying resistance to EGFR inhibitors such as gefitinib in non-small-cell lung cancer and other cancer types." (PMID 40725192, 2025). "Amphiregulin expression has also been reported in non-small cell lung carcinoma (NSCLC)-derived exosomes to induce osteoclast differentiation." (PMID 35453517, 2022). "Serum levels of the soluble epidermal growth factor receptor (sEGFR) and its ligands epidermal growth factor (EGF), transforming growth factor-α (TGF-α) and amphiregulin (AR) were measured in healthy donors and patients with non-small cell lung cancer (NSCLC) and head and neck carcinoma (HNC)." (PMID 17453000, 2007). "As reduced serum AREG levels correlated with longer progression-free survival of non-small-cell lung cancer patients treated with SBRT and immune checkpoint blockade, the potential of systemic AREG inhibition to delay tumor progression was evaluated." (PMID 40725192, 2025). "Indeed, EVs from the CRL-2868 non-small cell lung cancer (NSCLC) cell line and from lung cancer patients contain Amphiregulin (AREG) which in turn promotes osteoclast differentiation and exacerbated bone resorption by an EGFR-dependent mechanism." (PMID 34616676, 2021). "Notably, it was shown in patients with advanced non-small cell lung cancer that the survival time of amphiregulin-negative patients treated with gefitinib was significantly longer than that of amphiregulin-positive patients." (PMID 19529782, 2009).
rheumatoid arthritis (9 papers, 2008 to 2025). A chronic, systemic autoimmune disorder characterized by inflammation in the synovial membranes and articular surfaces. "Overexpression of Amphiregulin is associated with autoimmune diseases such as systemic lupus erythematosus, autoimmune diabetes, and rheumatoid arthritis." (PMID 39687011, 2024). "Intriguingly, cluster 2 also expressed AREG, which has been shown to be expressed by autoreactive B cells in rheumatoid arthritis patients." (PMID 40160682, 2025). "Amphiregulin (AREG) and epiregulin (EREG) are type II cytokines linked to a wide variety of inflammatory conditions, such as rheumatoid arthritis, chronic airway disease and glomerulonephritis." (PMID 34177613, 2021). "Human data indicate that both amphiregulin and epiregulin expressions were higher in bone marrow-derived mononuclear cells of rheumatoid arthritis patients and increased expression of amphiregulin was also detected in PBMCs and synovial tissues." (PMID 34615455, 2021). "AREG is involved in a variety of pathological processes, such as the development of tumors, inflammatory diseases, and rheumatoid arthritis." (PMID 25147440, 2014). "Furthermore, AREG expression has been identified in auto-reactive B cells in rheumatoid arthritis patients." (PMID 40160682, 2025). "Serum AREG and HB-EGF levels were measured by ELISA in patients with IIM (n = 37), systemic sclerosis (n = 17), and rheumatoid arthritis (n = 10), and for seven age- and sex-matched healthy controls (HCs)." (PMID 34442026, 2021). "Recombinant AREG upregulated the mRNA expression levels of vascular endothelial growth factor, IL-8, and IL-6, but not those of IL-1β or TNF-α in rheumatoid arthritis fibroblast-like synoviocytes." (PMID 37868614, 2023).